RNU1-32P (RNA, U1 small nuclear 32, pseudogene)
Gene: Small nuclear RNA gene on chromosome 2 (60,384,605 to 60,384,763, forward strand). Ensembl gene ENSG00000200807.
Homologues: Orthologues: chimpanzee U1 (99% identical), macaque U1 (91% identical), rabbit U1 (76% identical). Paralogues in human: RNU1-89P (89% identical), RNU1-1 (89% identical), RNU1-2 (89% identical), RNU1-27P (89% identical), RNU1-28P (89% identical), RNU1-3 (89% identical), RNU1-4 (89% identical), RNVU1-18 (89% identical), RNVU1-29 (89% identical), RNVU1-31 (89% identical), U1 (89% identical), RNVU1-28 (88% identical), and 134 more.